ENSG00000277124
Gene: Miscellaneous RNA gene on chromosome 7 (96,965,489 to 96,965,695, forward strand). Ensembl gene ENSG00000277124.
Gene Ontology:
Biological process: forebrain development; positive regulation of DNA-templated transcription